ACADVL (acyl-CoA dehydrogenase very long chain)
Description:
Catalyzes the first of the four reactions of the mitochondrial fatty acid beta-oxidation (FAO) pathway, which consists in the proR-proR stereospecific alpha, beta-dehydrogenation of fatty acyl-CoA thioesters using the electron transfer flavoprotein (ETF) as their physiologic electron acceptor, resulting in the formation of trans-2-enoyl-CoA ((2E)-enoyl-CoA). The mitochondrial FAO pathway is the major energy-producing process in tissues and is performed through cycles of four consecutive reactions. Each FAO cycle shortens the fatty acyl-CoA by two carbons, yielding one acetyl-CoA (for the citric acid cycle), one FADH(2), and one NADH (which donate electrons to the respiratory chain for ATP production). Among the different mitochondrial acyl-CoA dehydrogenases, very long-chain specific acyl-CoA dehydrogenase acts specifically on fatty acyl-CoAs with saturated 12 to 24 carbons long primary chains, but can also catalyze monounsaturated fatty acids such as oleate ((9Z)-octadecenoate), (9Z)-hexadecenoate, and others. Can use (4Z,7Z,10Z,13Z,16Z,19Z)-docosahexaenoate as substrate in vitro (which is not primarily used for energy but mainly beta-oxidized in the peroxisomes). In addition, based on its established catalytic mechanism, and combined genetic interaction or mutant phenotype evidence, it is predicted to act also on substrates that have not been tested experimentally but are metabolized by mitochondrial FAO, including long-chain unsaturated fatty acids such as linoleate (9Z,12Z-octadecadienoate), linolenate (9Z,12Z,15Z-octadecatrienoate), and others. Among the different mitochondrial acyl-CoA dehydrogenases, its FAO activity overlaps with that of ACAD9 and ACADL, but plays a primary role in tissues where it is the main long-chain ACAD expressed, such as the heart and skeletal muscle.
Synonyms: VLCAD; LCACD; ACAD6
Tractability: Small molecule: a structure with a bound ligand is known. Antibody: UniProt places it where antibodies can reach, with high confidence. PROTAC: ubiquitination databases record sites on it; its protein half-life has been measured; a small molecule that binds it is known.
Target class: Enzyme; Oxidoreductase
Gene: Protein-coding gene on chromosome 17 (7,217,125 to 7,225,269, forward strand). Ensembl gene ENSG00000072778.
Subcellular location: Mitochondrion inner membrane; Mitochondrion inner membrane (Isoform 2)
Subcellular location (Human Protein Atlas): Mitochondria; Nucleoli; Nucleoplasm
Pathways (Reactome):
Cellular responses to stimuli: XBP1(S) activates chaperone genes
Metabolism: Beta oxidation of palmitoyl-CoA to myristoyl-CoA
Gene Ontology:
Molecular function: acyl-CoA dehydrogenase activity; flavin adenine dinucleotide binding; identical protein binding; long-chain fatty acyl-CoA dehydrogenase activity; protein binding; very-long-chain fatty acyl-CoA dehydrogenase activity; fatty-acyl-CoA binding; medium-chain fatty acyl-CoA dehydrogenase activity; oxidoreductase activity, acting on the CH-CH group of donors
Biological process: epithelial cell differentiation; fatty acid beta-oxidation using acyl-CoA dehydrogenase; energy derivation by oxidation of organic compounds; negative regulation of fatty acid biosynthetic process; negative regulation of fatty acid oxidation; regulation of cholesterol metabolic process; temperature homeostasis; fatty acid beta-oxidation
Cellular component: mitochondrial membrane; mitochondrial nucleoid; mitochondrion; mitochondrial matrix; mitochondrial inner membrane
Genetic constraint (gnomAD): Loss-of-function variants: 73 observed, 82.38 expected, observed/expected ratio (o/e) 0.89, 90% interval 0.73 to 1.08. The upper end of that interval is the gene's LOEUF score, 1.08, which puts it in group 4 of 6, group 1 being the genes least tolerant of losing a copy. Missense variants: 878 observed, 886.23 expected, observed/expected ratio (o/e) 0.99, 90% interval 0.94 to 1.05. Synonymous variants: 392 observed, 335.33 expected, observed/expected ratio (o/e) 1.17, 90% interval 1.08 to 1.27.
Gene-disease validity (ClinGen):
ClinGen rates the evidence that ACADVL causes each of these diseases.
very long chain acyl-CoA dehydrogenase deficiency (autosomal recessive): Definitive. An inherited disorder of mitochondrial long-chain fatty acid oxidation with a variable presentation including: cardiomyopathy, hypoketotic hypoglycemia, liver disease, exercise intolerance and rhabdomyolysis.
Homologues: Orthologues: chimpanzee ACADVL (97% identical), macaque ACADVL (96% identical), dog ACADVL (90% identical), pig ACADVL (85% identical), rat Acadvl (85% identical), rabbit ACADVL (84% identical), mouse Acadvl (84% identical), guinea pig ACADVL (80% identical), zebrafish acadvl (70% identical), tropical clawed frog acadvl (65% identical), Drosophila melanogaster Acadvl (52% identical), Caenorhabditis elegans acdh-12 (44% identical). Paralogues in human: ACAD9 (43% identical), ACADS (22% identical), ACADSB (21% identical), ACADM (20% identical), IVD (19% identical), ACAD8 (19% identical), ACADL (18% identical), GCDH (18% identical), ACAD10 (18% identical), ACOX3 (17% identical), ACAD11 (16% identical), ACOX1 (15% identical), and 2 more.